IDH1 (isocitrate dehydrogenase (NADP(+)) 1)
Diseases named in the same sentence as IDH1 in open-access papers (continued):
Sharing a sentence is not in itself a finding about the gene and the disease.
cancer (continued). "General attention paid to mitochondrial nuclear-encoded gene mutations has greatly emerged since the defects of fumarate hydratase, succinate dehydrogenase, isocitrate dehydrogenase 1 (IDH1), and IDH2 in cancer cells were established." (PMID 36557887, 2022). "The MCODE analysis identified gene clusters for each cancer type with MYC, PCNA, PARP1, IDH1, FGF10, PTEN, and CCND1 as hub genes with high connectivity." (PMID 35001007, 2022). "Mutations in the two isocitrate dehydrogenase enzymes involved in cytoplasmic (IDH1) and mitochondrial (IDH2) conversion of alpha-ketoglutarate to D-2-hydroxyglutarate have been described as mutually exclusive in many of these cancer types." (PMID 36304962, 2022). "Of note, It was revealed that the expression of most genes was generally consistent with results of TCGA cancer set, such as TRIM24, HMG20B, CBX6, IDH1, RCC1, RYBP, CBX7, and LBR." (PMID 36246611, 2022). "As the most well-known recent biomarker in the cancer research field, PD-L1, also named CD274, was found to be upregulated in IDH1/2 wild-type GBM." (PMID 33621203, 2021). "Although IDH1 and IDH2 are highly similar and catalyze identical reactions, their expression differs in different cancers and their subtypes." (PMID 34638714, 2021). "We also note that IDH1 plays a key role in NADPH production and acts as a potential regulator of lipid metabolism in cancer cells and in virus-infected cells with reductive metabolism." (PMID 31555294, 2019). "A dataset comprising 200 IDH1 wild-type GBM patients, derived from The Cancer Imaging Archive (TCIA) (n = 71) and the McGill University Health Centre (n = 129), was used in this study." (PMID 31405148, 2019). "Once again, we can consider how cancer cells avoid death when confronted by damaging stress conditions, because, as we have shown for NSUN5, the disruption of IDH1 is another way of dealing with metabolic and hypoxic stress." (PMID 31428936, 2019). "In the same cancer type, small molecule GSK864-mediated inhibition of IDH1 favors less differentiated tumor formation and promotes progression of GBM." (PMID 31288436, 2019). "Notably, mutant IDH1/2 inhibitors are being evaluated in Phase I/II clinical trials with inhibitors of DNMTs, with the rationale being that they might promote active DNA demethylation and suppress DNA methylation, respectively, to reverse DNA methylation in IDH1/2-mutant cancers." (PMID 28092669, 2017). "Cancer cells regulate NADPH homeostasis through multiple pathways such as the PPP and the flux through ME1 and IDH1 in the cytoplasm." (PMID 28481367, 2017). "Thus, the decrease in 5hmC may not correlate with IDH1/2 mutations, at least in the cancer specimens we tested." (PMID 26462176, 2015). "In the TCA cycle, IDH1/2 and malic enzyme 1 (ME1), of which the levels are altered in many type of cancer cells, contribute to NADPH production." (PMID 26008980, 2015). "It has been shown that NR4A1 maintains low levels of stress in cancer cells by regulating expression of TXNDC5 and IDH1 that in turn maintain high levels of cellular reducing agents." (PMID 26035713, 2015). "We investigated the function of D-2-HG in tumorigenesis using IDH1 and IDH2 mutant cancer cell lines." (PMID 25825982, 2015). "Mutations in these genes appear to be either specific to ICC, as is the case of IDH1 and IDH2 (p=0.0005), or cluster within this cancer type as is the case for ARID1A, BAP1, and PBRM1 that were found in 34.3% (24/70) of ICC." (PMID 24867389, 2014).
cancer (continued). "As we previously discussed, several epigenetic modifiers such as EZH2, IDH1/2, and DNMT3A are genetically altered in cancer." (PMID 23533770, 2013). "To confirm this finding and expand it to the other IDH mutants found in gliomas, we measured 2HG levels in media incubated with HOG cells overexpressing IDH1-WT, IDH2-WT, or one of the recurrent cancer-derived mutants." (PMID 21326614, 2011). "We studied C. elegans cytoplasmic isocitrate dehydrogenase (IDH-1, NP_001255393.1) to determine if it could be a good model for studying the effects of dominant mutants of human IDH1 (NP_001269316.1) in cancer development." (PMID 40943163, 2025). "We found that the IDH1 inhibitor ivosidenib functions as an HR repair inhibitor by targeting YTHDC2, and a combination treatment of ivosidenib and PARPi Olaparib produced synergistic anti-tumor effects in BRCA1/2-proficient cancer cells." (PMID 40299557, 2025). "Except for IDH1-132, which is well-known in LGG and GBM, no other hotspot demonstrated significance in more than one cancer type, indicating that hotspots associated with survival in the “vs. All” test are specific to each cancer type." (PMID 38473427, 2024). "Indeed, ME1 has been found increased in different kinds of cancers as well as IDH1 and glucose-6-phosphate-dehydrogenase (G6PD), likely preserving cancer cells from excessive reactive oxygen species (ROS) levels and in turn damage to molecules and apoptosis." (PMID 39335602, 2024). "This is probably due to the nature of the mutations, which, unlike IDH1 and IDH2 mutations, are primarily inactivating mutations and, therefore, do not result in the cancer cell acquiring new functions." (PMID 39063158, 2024). "While mutated IDH1 and IDH2 are cancer-driver genes through the production of 2-HG and its impact on the epigenome, IDH3 has not been characterized as such in cancer." (PMID 37601653, 2023). "For example, they observed that while IDH1 mutations conferred a protective effect against increased VTE risk in glioma patients this was not the case for other cancers." (PMID 38188342, 2023). "Mechanistically, we showed that when cancer cells experienced nutrient withdrawal, the RNA binding protein Hu antigen R/ELAV like RNA-binding protein 1 (HuR), positively regulates wild-type IDH1, to increases antioxidant defense and overcome these harsh conditions." (PMID 36153582, 2022). "Cancer types that displayed the largest differences between groups were LGG (IDH1 1% in the low- versus 95% in the high-methylation group), GBM (IDH1 0% versus 88%), LAML (IDH1 6% versus 56%; IDH2 3% versus 44%) and KIRC (SETD2 0% versus 36%)." (PMID 35134107, 2022). "Nevertheless, a prominent status of the IDH1 and IDH2 mutations has never been undertaken particularly within a large number of different human cancer samples." (PMID 35996504, 2021). "Furthermore, various mutations in Krebs cycle enzymes, including succinate dehydrogenase (SDH), fumarate hydratase (FH), and isocitrate dehydrogenase 1 (IDH1) and 2 (IDH2), are described in cancer cells." (PMID 34445360, 2021).
cancer (continued). "In conclusion, the development of oral, potent, small molecule and mutant specific IDH1 and IDH2 inhibitors represents an early success story of the cancer genome-sequencing era, and signifies an important advance for AML therapy in the era of personalized therapeutics." (PMID 34083508, 2021). "IDH1/2 and TET2 mutations are not mutually exclusive but rather coexist in a large fraction of patients in some cancers such as AITL." (PMID 33805247, 2021). "At present, small molecular inhibitors of IDH1 and IDH2 mutant have been developed, and promising progress has been made in preclinical and clinical development, showing encouraging results in patients with IDH2 mutant cancers." (PMID 33981605, 2021). "Several recent advances in IDH1 mutant mouse models have been developed, which are discussed in our recent review, along with increased evidence reflecting the potential value of targeting mutant IDH in cancer treatment." (PMID 32825279, 2020). "The multitargeted activity of these compounds makes them valuable agents against a wide range of cancers, regardless of the status of IDH1." (PMID 32110969, 2020). "IDH1 had the highest ConsensusDriver score, as evident in LGG, and this ERG showed a driver role in six other cancer types, which explains why it additionally had the highest pan-cancer ConsensusDriver score (PANCAN)." (PMID 32963031, 2020). "Of which, 660 genes were well-known cancer genes, such as CTNNB1, IDH1." (PMID 33240890, 2020). "Notch3 silencing in MCF7 and TFK1 cells results in Mdh1, Idh1 and Ido1 down-representation, as observed in HepG2 and Huh7 HCC cell lines, suggesting that Notch3 regulation of metabolic pathways is a common feature in different human cancer cells." (PMID 30765875, 2019). "Here, we summarize studies reporting on aberrant IDH1, IDH2, and IDH3 expressions in cancers." (PMID 31010244, 2019). "To date, no study has reported cancer-associated mutations in IDH3, although IDH3 has a similar function as that of IDH1 and IDH2." (PMID 31660152, 2019). "Whether IDH1/2 follows a similar strategy to ACO1 or TYMS, and whether it plays key roles in cancer development will be important to explore." (PMID 29216518, 2018). "Further, siRNA knockdown studies of IDH1 and IDH2 resulted in slow a growth of cancer cells." (PMID 29439493, 2018). "For example, known disease genes BRCA2, CDH1, IDH1, CDKN2A, NME1 and FGFR3 frequently occurred at the top one in seven cancer types (including BC, GC, GBM, MB, MM, NB and OC), even though only two or three known-disease genes existed in NB, GBM and MB gene lists." (PMID 28076842, 2017). "It is worth mentioning here that, theoretically, decreasing intracellular 2KG level might have a deleterious effect on the 2KG requiring dioxygenases that are already inhibited in IDH1 R132 and IDH2 R172 mutant cancer." (PMID 28785398, 2017). "Furthermore, IDH1 catalyzes the production of NADPH, the levels of which limit the growth and survival of cancer cells." (PMID 27655638, 2016). "Previous work has demonstrated that cancer cells are capable of adapting to mitochondrial dysfunction by engaging IDH1-dependent reductive carboxylation of α-KG rather than conventional oxidation in the TCA cycle." (PMID 26625127, 2015). "IDH1- and IDH2-mutant cancer cells aberrantly accumulate D2-hydroxyglutarate (D2-HG)." (PMID 26178471, 2015).
cancer (continued). "When using SNVs only, most such genes were known cancer genes, such as U2AF1, IDH1, and DNMT3A in LAML (FLT3 SNVs cluster within five amino acids), AKT1 and KRAS in BRCA, BRAF and KRAS in COADREAD, IDH1 and PARG (poly (ADP-ribose) glycohydrolase) in GBM, and KRAS in UCEC." (PMID 25348067, 2014). "Although IDH1 mutations have been reported in colon cancer, no IDH2 mutations in this cancer subtype have been identified to date." (PMID 23226729, 2012). "Since binding to IDH1-WT may be an important function for IDH1 R132 mutants in cancer, we hypothesized that IDH2 R172 mutants may localize outside the mitochondria and also bind IDH1-WT." (PMID 21326614, 2011). "However, the majority of human cancers do not contain TET1, TET2, TET3, IDH1, or IDH2 mutations and, still show a reduced 5hmC compared to the corresponding normal tissue." (PMID 40537872, 2025). "However, this same vulnerability also raises therapeutic challenges; for instance, using IDH1 inhibitors during radiotherapy may restore NADPH pools, unintentionally shielding cancer cells from ROS-based treatments." (PMID 40724998, 2025). "Therefore, serine-mediated one-carbon metabolism compensates for G6PD loss in KL cancer cell survival, although this does not preclude the potential compensatory cytosolic NADPH production through ME1 or IDH1." (PMID 38997257, 2024). "IDH1 mutations in CAC (7% in both IBD dysplasia and CAC; not reported in non-dysplastic IBD colon) follow hotspots observed in other cancers, such as gliomas, that result in accumulation of the 2-hydroxyglutarate oncometabolite (2-HG) which results in a hypermethylation phenotype." (PMID 37884500, 2023). "In contrast to findings with PDAC cells, IDH1 upregulation did not occur in a noncancer cell line cultured under glucose withdrawal, raising the possibility that this enzyme is particularly important to cancer cells." (PMID 35681100, 2022). "However, the negative effect of IDH1-R132H on drug resistance in cancer chemotherapy has been reported in several recent publications." (PMID 35802554, 2022). "A peptide vaccine targeting IDH1R132H (IDH1-vac), previously established in MHC-humanized mouse models, has been successfully tested in a phase I first-in-human multicenter clinical trial by the Neurooncology Working Group (NOA) of the German Cancer Society (NOA-16 trial)." (PMID 35599302, 2022). "In the future, it will be important to study whether and how IDH1 regulates other key steps of translation besides initiation and to explore this non-canonical function in cancer and cellular responses." (PMID 31504662, 2019). "In animal experiments, it was found that IDH1 mutant cancer cells could be prevented from growing in the brain, and the vaccine did not destroy the normal physiological function of the IDH1 enzyme." (PMID 31263678, 2019). "Therefore, the disruption of the normal functions of IDH1 and IDH2 may significantly affect the cellular redox balance and result in cancer cell growth dysfunction." (PMID 29661250, 2018). "The mechanism of low IDH1 participates in progression of cancers has not been well elaborated." (PMID 30153799, 2018). "While mutations have been observed in IDH1 and IDH2, IDH3 mutations have not been found in cancer." (PMID 29342092, 2018). "Ongoing clinical trials are testing the anticancer activity of specific inhibitors of IDH1 and IDH2 mutant enzymes and a positive outcome would support the concept of oncometabolites, thereby providing a productive new example of targeted therapy against cancer metabolism." (PMID 27635066, 2016). "The mechanisms of IDH1 regulation and effects on cancer have not been elaborated." (PMID 27863386, 2016). "The relative importance of either dominant negative activity or 2HG-producing catalytic activity for the IDH1 and IDH2 mutants in cancer is unclear, and the mechanism by which either of these gained functions may contribute to cancer pathogenesis remains unknown." (PMID 21326614, 2011).
cancer (continued). "Microsatellite instability and BRAF/IDH1 mutations were rare or absent events in our series and unrelated to the CIMP phenotype, suggesting that the mutational processes linked with CIMP phenotype in MPM may differ from those of other cancers." (PMID 36928603, 2023). "Also, in contrast to IDH1 and IDH2, the heterotetrameric IDH3 is not subjected to cancer mutations." (PMID 29439493, 2018). "IDH3 is not as well characterized as IDH1 and IDH2 in the context of cancer and other diseases; however, more recent studies implicate aberrant expression of IDH3—especially the alpha subunit—in malignancy." (PMID 36549590, 2023). "Moreover, Rac1 and Rictor suppression led to cell viability decrease in IDH1-mutated U251 cells and BTIC TS603, but not in IDH1 wild type U251 cells and BTIC GSC923, which indicates that targeting of the mTORC2/Rac1 pathway might be a potential therapeutic approach for cancers with IDH1 mutations." (PMID 32224866, 2020). "Intriguingly, our simple correlation of clinical variables with intron retention suggested that mutations affecting factors not canonically involved in RNA processing, such as IDH1 and IDH2, may contribute to splicing dysregulation in cancer." (PMID 26113877, 2015).